OR2A5 (olfactory receptor family 2 subfamily A member 5)
Description:
Odorant receptor.
Synonyms: OR7-138; OR7-141; OR2A26; OR2A8; OR2A11P
Tractability: Antibody: UniProt places it where antibodies can reach, with medium confidence; UniProt predicts a signal peptide or a membrane-spanning region; its Gene Ontology location is reachable by antibodies, with medium confidence.
Gene: Protein-coding gene on chromosome 7 (144,048,948 to 144,058,845, forward strand). Ensembl gene ENSG00000221836.
Subcellular location: Cell membrane
Pathways (Reactome):
Sensory Perception: Expression and translocation of olfactory receptors
Gene Ontology:
Molecular function: olfactory receptor activity; G protein-coupled receptor activity
Biological process: detection of chemical stimulus involved in sensory perception of smell; G protein-coupled receptor signaling pathway
Cellular component: plasma membrane; membrane
Genetic constraint (gnomAD): Loss-of-function variants: 8 observed, 12.25 expected, observed/expected ratio (o/e) 0.65, 90% interval 0.38 to 1.18. The upper end of that interval is the gene's LOEUF score, 1.18, which puts it in group 5 of 6, group 1 being the genes least tolerant of losing a copy. Missense variants: 391 observed, 388.29 expected, observed/expected ratio (o/e) 1.01, 90% interval 0.93 to 1.1. Synonymous variants: 160 observed, 160.53 expected, observed/expected ratio (o/e) 1, 90% interval 0.88 to 1.14.
Homologues: Orthologues: chimpanzee OR2A5 (99% identical), dog OR2A5 (89% identical), mouse Or2a5 (86% identical), rat Or2a5 (86% identical), macaque OR2A5 (74% identical). Paralogues in human: OR2A1 (79% identical), OR2A42 (79% identical), OR2A14 (79% identical), OR2A12 (76% identical), OR2A2 (72% identical), OR2A25 (67% identical), OR2A7 (65% identical), OR2A4 (65% identical), OR7C2 (45% identical), OR5BS1 (45% identical), OR4S2 (44% identical), OR10R2 (44% identical), and 116 more.
Diseases named in the same sentence as OR2A5 in open-access papers:
OR2A5 is named in the same sentence as 2 diseases in open-access papers, as found by Europe PMC text mining. Sharing a sentence is not in itself a finding about the gene and the disease. The quoted sentences say what the papers report.
colon adenocarcinoma (1 paper, 2022). "Mutations of SKIDA1, CLK1, NSFL1C, OR2A5, EDEM3, and OR51V1 were associated with significant deregulation of DDX20 gene expression pattern in colon adenocarcinoma patients." (PMID 36011315, 2022).
prostate carcinoma (1 paper, 2022). A carcinoma that arises from epithelial cells of the prostate gland. "Lin and colleagues found results in agreement with our study, where OR2A5 was also related to the risk of developing prostate cancer." (PMID 35741800, 2022).